IDH1 (isocitrate dehydrogenase (NADP(+)) 1)
Diseases named in the same sentence as IDH1 in open-access papers (continued):
Sharing a sentence is not in itself a finding about the gene and the disease.
astrocytomas (continued). "On the other hand, ATRX mutations are mutually exclusive from 1p19q co-deletion, but are associated with IDH1 mutation, suggesting that ATRX drives the lineage-specific formation of astrocytomas." (PMID 32120790, 2020). "The median expression differed from 8.0 ng/mL (range: 2.3 to 19.6) in the control group to 13.8 ng/mL (range: 7.3 to 46.4) in the high-grade IDH1-wildtype astrocytoma group." (PMID 33227903, 2020). "Nevertheless, included IDH1 wild type astrocytomas showed characteristic deletions of chromosome 10 and duplications of chromosome 7 that strongly contributed to the formation of a separate major middle subgroup." (PMID 32604718, 2020). "Figure A2, Rapamycin, through its mTORC1 inhibition, is an effective killer of 2 IDH1 wt GBMSC and of 1 IDH1 mutant GBMSC and another IDH1 mutant grade III astrocytoma stem cell line." (PMID 33255358, 2020). "Expression of IDH1 R132H assessed by IF in the astrocytomas was too weak to be quantified accurately." (PMID 32218467, 2020). "A subgroup like astrocytoma shared less difference of OS among patients when TMZ was used with IDH1 mutant (log rank = 0.9) while the same histology patients had relatively better OS for IDH wild-type phenotypes (log-rank p = 0.09)." (PMID 33552543, 2020). "We derived and validated cell cultures from IDH1-mutant recurrences of astrocytoma and oligodendroglioma." (PMID 32904945, 2020). "The results of this study strongly suggests that Raman spectroscopy enables to distinguish IDH1-mut astrocytoma and oligodendroglioma—which differ for the presence of 1p/19q codeletion—thus showing potential for diagnostics." (PMID 31750251, 2019). "BAY1436032, a pan inhibitor of IDH1 R132H, significantly prolongs the survival of human astrocytoma (IDH1 R132H)-bearing mice." (PMID 31652645, 2019). "Patients with IDH1-mutant astrocytomas can expect a better prognosis than can patients with IDH1-wild type astrocytomas of different grades." (PMID 31275753, 2019). "A similar, but independent study reported that long-term AZA treatment shows significant tumor regression in a mouse xenograft of IDH1-mutant astrocytoma model." (PMID 31652645, 2019). "p.IDH1-R132H mutations were found in 7 samples, all diagnosed as grade II/III astrocytomas and oligodendrogliomas." (PMID 31747973, 2019). "Oligodendroglioma and astrocytoma IDH1-mutant, which differ in the presence of 1p/19q codeletion, were discerned with a correct rate of 81%." (PMID 31750251, 2019). "Mutations in IDH1 or IDH2 are found in 100% of oligodendrogliomas, 70–80% of lower grade astrocytomas, and in secondary glioblastoma." (PMID 30823903, 2019). "First reported results showed that NOA-16 demonstrated safety and immunogenicity of a mutant IDH1-R132H peptide vaccine in patients with newly diagnosed IDH1-R132H malignant astrocytomas." (PMID 30857299, 2019).
astrocytomas (continued). "Periostin expression was increased in secondary GBMs when compared to R132H IDH1 low-grade astrocytomas." (PMID 31052505, 2019). "Five patients had an IDH1-mutant astrocytoma and were, based on that information, classified as having no 1p/19q codeletion." (PMID 30094719, 2018). "By performing this analysis, it was clearly shown that IDH-wildtype astrocytoms preferentially localized in the white matter, and IDH1/2-mutant astrocytomas in the frontal, insular, and temporal lobe." (PMID 30082856, 2018). "Large-scale sequencing studies revealed that heterozygous mutations in both cytosolic IDH1 and mitochondrial IDH2 are highly prevalent in World Health Organization (WHO) grade II and III astrocytomas or oligodendrogliomas and in secondary glioblastomas." (PMID 29567975, 2018). "IDH1 and IDH2 genes mutations play a prominent role in gliomagenesis, specific to both oligodendrogliomas and astrocytomas." (PMID 29099032, 2017). "When combining IDH1-R132H with ATRX loss as diagnostic biomarkers for discriminating between pGBM, oligodendroglioma (WHO grade II/III) and sGBM, astrocytoma (WHO grade II/III), the AUC was 0.7407 (sensitivity 53.33%, specificity 94.815%)." (PMID 26918938, 2016). "In this study, we investigated the expression of FilGAP, with reference to the status of its related molecules, including FLNa, integrin β2, and Rac1, as well as the expression of ECT 2, cell proliferation, and IDH1 gene status in astrocytomas." (PMID 27790861, 2016). "In this analysis of low-grade astrocytomas stratified for IDH1, extensive tumor resections were prognostic for progression and TTR and, in patients with ≥40 % EOR, for OS." (PMID 27344556, 2016). "In our study, we also showed that decreased ATRX mRNA expression was characteristically enriched in low-grade astrocytomas and this ATRX alteration significantly overlapped with IDH1/2 mutations (P<0.0001)." (PMID 24810474, 2014). "More recently, the NADP+ -dependent enzyme IDH1 was found to be mutated in ∼70% of grade II and grade III astrocytomas and oligodendrogliomas, and secondary GBMs." (PMID 25147764, 2014). "In particular, 13.6% (12/88) of Grade II-III astrocytomas bore TERT promoter mutations alone and occasional Grade II-III astrocytomas harbored both TERT promoter and IDH1/2 mutations (4/88, 4.6%)." (PMID 24722048, 2014). "IDH1/2 mutations were much less prevalent among GBMs (10%), and much more common in Grade II-III astrocytomas (78.4%), oligoastrocytomas (86.2%) and oligodendrogliomas (96.5%)." (PMID 24722048, 2014). "A large-scale study revealed IDH1 mutations in 50% to 80% of patients with grade 2 astrocytoma, oligodendroglioma, or secondary GBM; however, IDH1 mutations were rare in patients with primary GBM." (PMID 24160898, 2013). "Patients with IDH1 wild-type astrocytomas had shorter OS (median 65 months) and PFS (median 33.9 months) than those with IDH1mutated astrocytomas (median OS 23 months, p<0.001; median PFS 14 months, p = 0.001)." (PMID 23840696, 2013).
astrocytomas (continued). "Further analysis in astrocytomas (AII and AAIII) revealed the association between IDH1 mutation and prognostic outcome." (PMID 23840696, 2013). "In summary, IDH1 is a sufficient marker that allows a better separation of primary GBM from other malignant astrocytomas than any other marker and will help to define more accurately this tumor entity in upcoming studies." (PMID 21910919, 2011). "The Kaplan–Meier survival curves showed that patients reclassified from GBM to IDH1/2-mutant astrocytoma (n = 45) had significantly better survival than those with IDH1/2-wild-type GBM (n = 285), but worse survival than patients with IDH1/2-mutant astrocytoma (n = 179) (P < 0.0001)." (PMID 41377022, 2025). "Importantly, the vaccine demonstrated favorable safety profiles and robust immunogenicity, with evidence of improved clinical outcomes in IDH1-mutant astrocytoma cohorts." (PMID 40661781, 2025). "In conclusion, seizures in patients with astrocytomas are associated with IDH1 and NMDA receptor mutations, rather than other clinicopathological factors or other glutamate-related genes." (PMID 40718831, 2025). "A more recent study reported that PIK3R1 is uniquely overexpressed in IDH1-mutant grade 4 astrocytoma, indicating that combined targeting of the PI3K/AKT/mTOR pathway and the immune system may be necessary for effective treatment in this subtype." (PMID 40504311, 2025). "Between 2017–2021, the incidence rate of IDH1/2 mutant astrocytoma was 0.46 per 100,000 population." (PMID 40949165, 2025). "The neuropathological tumor diagnosis was astrocytoma, IDH1 mutant, CNS WHO grade 2." (PMID 41319210, 2025). "Notably, vorasidenib is now approved for the treatment of Grade II IDH1- or IDH2-mutant astrocytomas, marking a significant advancement in targeted therapy." (PMID 40223032, 2025). "Amongst IDH1/2-mutant astrocytoma in the non-TCGA cohort, CDKN2A/B loss (hemizygous or homozygous) was the strongest negative prognostic feature (HR: 2.81, 95%CI: 1.8–4.4) after adjusting for demographic, molecular, and treatment variables." (PMID 39584448, 2025). "In IDH1/2-mutant astrocytomas, isolated 19q variations were identified in 19.0% of cases." (PMID 41377022, 2025). "In contrast, patients with astrocytomas who had recently experienced seizures had significantly higher levels of IDH1 mutations than those who did not have seizures (6/14 vs. 2/20; p = 0.04)." (PMID 40718831, 2025). "Furthermore, grade 4 IDH1/2-mutant astrocytomas showed a greater genomic distance from grade 2/3 IDH1/2-mutant astrocytomas than between grades 2 and 3 IDH1/2-mutant astrocytomas (P < .001)." (PMID 39164213, 2025). "The fifth edition of the World Health Organization Classification of Tumors of the Central Nervous System requires identifying IDH1 or IDH2 mutation without 1p19q co-deletion for diagnosing an astrocytoma." (PMID 39906460, 2025). "IDH-mutant astrocytomas are diffuse gliomas that are defined by characteristic mutations in IDH1 or IDH2 and do not have complete 1p/19q co-deletion." (PMID 39899075, 2025). "profiled the immune landscapes of IDH1 WT GB versus IDH1 mutant astrocytoma." (PMID 40642066, 2025). "Finally, the focal amplifications included as part of this analysis represent a subset of prognostically significant amplifications described for IDH1/2-mutant astrocytomas, such as MYCN." (PMID 39584448, 2025). "Given the prognostic role of both CDKN2A/B loss and focal amplifications, we sought to determine whether these two molecular markers could be integrated to refine the histopathologic stratification of IDH1/2-mutant astrocytoma." (PMID 39584448, 2025). "Notably, IDH1 and IDH2 gene mutations serve as a hallmark genetic alteration in astrocytomas linked to CIN." (PMID 39227895, 2024). "Regarding PFS and OS IDH1/2 wt astrocytomas, WHO III behave like WHO grade IV tumors." (PMID 38326661, 2024).
astrocytomas (continued). "Histology confirmed a WHO Grade 2, IDH1-positive astrocytoma." (PMID 39239149, 2024). "The authors assessed tumours for 1p/19q deletion if they were not morphologic astrocytomas and assessed all tumours for IDH1/2 mutations by genome sequencing." (PMID 37504251, 2023). "This molecular mechanism in disease progression seems analogous to IDH1-mutant astrocytoma." (PMID 38012788, 2023). "IDH-mutant tumors, thus, have a better prognosis than IDH1/2 wildtype astrocytomas." (PMID 36604386, 2023). "The presence of an IDH1 or IDH2 mutation and an unbalanced translocation between chromosomes 1 and 19 (1p/19q-codeleted) classifies oligodendrogliomas, whereas an IDH1/2 mutation without 1p/19q-codeletion defines astrocytomas." (PMID 37958846, 2023). "It has been demonstrated that PDGFRA amplification is correlated with IDH1 mutation and associated with poorer prognosis in IDH1-mutant astrocytomas, CNS WHO grade 4, as compared to those without PDGFRA amplification." (PMID 38012788, 2023). "Moreover, Gal-1 levels were significantly lower in grade 4 IDH-1 mutant astrocytomas, which have a better prognosis." (PMID 36980184, 2023). "Similar to IDH-mutant astrocytomas, IDH1 R132H represents the most common mutation in oligodendrogliomas, although non-canonical mutations in IDH2 at codon 172 are more common in oligodendrogliomas compared to astrocytomas." (PMID 37239289, 2023). "Curiously, astrocytomas present often non-canonical IDH1 mutations that are associated with improved survival." (PMID 35875065, 2022). "Moreover, RFC2 expression was obviously increased in LGG samples with WHO III grade (P < 0.001), astrocytoma (P = 0.041 and P = 0.023), and IDH1 wild-type (P < 0.001)." (PMID 35210438, 2022). "Additionally, several IDH1 inhibitors are being tested for treatment of IDH-mutant astrocytomas, including ivosidenib and enasidenib." (PMID 36147920, 2022). "The identification of cystathionine in IDH1-mut astrocytoma in our study might indicate that this MRS parameter reflects the presence of IDH1 mutation." (PMID 34941573, 2022). "IDH1-vac safely targets IDH1R132H in newly diagnosed astrocytomas." (PMID 35599302, 2022). "Indeed, the long cell processes highlighted by IDH1 R132H IHC imply fundamentally more mature tumor cells in this case than are usually encountered in IDHmut astrocytomas." (PMID 35128400, 2022). "Astrocytoma, IDH-mutant is a highly malignant astrocytic glioma with a low survival rate (6.8% survival rate post-diagnosis, median survival of 8 months) and portrayed mutations to either IDH1/2." (PMID 36467419, 2022). "Importantly, we noted that the mutant form of IDH1, which is the factor of a good astrocytoma patient survival prognosis, was found in GBM tumors with an increased expression of miR-181a." (PMID 36232448, 2022). "Another finding was the detection of higher cystathionine levels in IDH1-mut astrocytoma." (PMID 34941573, 2022). "Histological review in the primary analysis of the trial material classified 58 out of 59 samples included in this study as GBM grade 4, and one sample was classified as astrocytoma grade 3, but all samples were IDH1 mutation-negative." (PMID 36092918, 2022). "H3K27me3 retention was observed in 87% (26/30) of IDH1 Mut astrocytomas (25/29 IDH1-R132H, 1/1 IDH1-R132S) regardless of the mutation type." (PMID 34020723, 2021).
astrocytomas (continued). "Likewise, the IDH-wildtype astrocytoma classified as (anaplastic) pleomorphic xanthoastrocytoma harbored a BRAF V600E mutation and was IDH1-wildtype detected by Sanger sequencing." (PMID 33941250, 2021). "Furthermore, in IDH1-mutant GBMs, STOX1 was significantly downregulated compared to IDH1-mutant astrocytomas (Figure A1c and d)." (PMID 34722888, 2021). "Cases #4 and #5 were WHO grade II astrocytomas, IDH1-mutant." (PMID 34685506, 2021). "While, the 1p19q non-co deleted tumors are classified as astrocytomas with or without IDH1/2 mutation and have more “circumscribed” margins and display the (T2-FLAIR mismatch) pattern." (PMID 34676470, 2021). "In their series, patients harboring a non-canonical IDH1 mutation were more frequently astrocytomas (65.6 vs. 43%), while patients with IDH1 mutations were often oligodendrogliomas (85 vs. 48.3%)." (PMID 33669525, 2021). "While the loss of nuclear H3K27me3 was predominantly seen in IDH1-R132H Mut oligodendrogliomas, retained nuclear staining was mostly observed in IDH1 Mut astrocytoma regardless of the mutation type." (PMID 34020723, 2021). "Interestingly, the only patient with HGG also bearing mutant IDH1 (astrocytoma, CNS WHO grade 3) had the lowest mean NAD(H) intensity, suggesting a relation between the NAD(H) level in tumor tissue and the IDH mutation status." (PMID 35002914, 2021). "Furthermore, no significant expression difference was observed for the MGMT gene between IDH1 mutant and wild type astrocytomas (q = 0.87)." (PMID 32604718, 2020). "In this study, we analyzed molecular profiles of patient-matched tumors pairs of 22 astrocytoma patients with and without IDH1 mutations." (PMID 32604718, 2020). "In addition, we also conducted tests on an IDH1 mutant Grade III astrocytoma patient-derived cell line in the appendix figures." (PMID 33255358, 2020). "On the other hand, the great majority of WHO grade IV astrocytomas falls into the IDH1-wildtype category (more than 90% of cases), which corresponds most frequently to the clinically defined primary GBM resulting in poor prognosis even with intensive treatments." (PMID 32382870, 2020). "The other case (#35) was the recurrence of an IDH1 p.R132H grade II astrocytoma." (PMID 32642724, 2020). "Although the IDH1 mutation has been considered a hallmark of astrocytoma and a good prognosis, an IDH1 mutation was not identified until the late stage (relapse tumor, WHO IV)." (PMID 32069381, 2020). "To molecularly characterize foci found in DLGG patients, we selected 8 tumours with mutations for IDH1 (IDH1 R132H) with and without 1p19q co-deletion (4 oligodendrogliomas and 4 astrocytomas respectively)." (PMID 32218467, 2020). "Furthermore, approximately one-quarter (27.7%) of all high-grade IDH1-wildtype astrocytoma patients had higher CHI3L1 protein concentrations in serum than the highest CHI3L1 value in the control group (66.1 ng/mL)." (PMID 33227903, 2020). "Furthermore, we observed that IDH1 mutant astrocytomas were positively correlated with the G-CIMP subtype, whereas IDH1 wild type astrocytomas showed either negative or only weak positive correlations." (PMID 32604718, 2020). "Furthermore, the pentose phosphate and the valine, leucine, and isoleucine biosynthesis pathways were also enriched for underexpressed genes in IDH1 mutant astrocytomas." (PMID 32604718, 2020).